CYBB (cytochrome b-245 beta chain)
Diseases named in the same sentence as CYBB in open-access papers (continued):
Sharing a sentence is not in itself a finding about the gene and the disease.
Hyperglycemia (53 papers, 2013 to 2026). An increased concentration of glucose in the blood. "Polymorphisms in CYBB (NOX2), NCF1 (p47phox), and NCF2 (p67phox) may differ from Caucasian or Asian populations, potentially modulating basal NOX2 activity and response to hyperglycemia." (PMID 41607455, 2026).
Obesity (47 papers, 2012 to 2025). Accumulation of substantial excess body fat. "The hub genes calculated by Cytoscape software are MNDA (score 320), CYBB (score 314), CD86 (score 312), FCGR2C (score 242), NCF2 (score 240), LCP2 (score 182), TLR8 (score 148), HLA-DRA (score 54), LCP1 (score 30), and PTPN22 (score 8), which are considered to be associated with obesity-related AF." (PMID 36671813, 2023).
COVID-19 (44 papers, 2020 to 2025). A disease caused by infection with severe acute respiratory syndrome coronavirus 2. "CYBB is a co-regulated gene in COVID-19 and NAFLD and is also involved in encoding cytochrome b-245, which is an important component of NADPH oxidase." (PMID 37335656, 2023). "CYBB, also named NADPH oxidase (mainly Nox2), was proven to play a crucial role in vascular and cerebral oxidative stress and inflammation, and Nox2 activation stimulates oxidative stress and associates with a severe course and thrombotic events in COVID-19 patients." (PMID 36547446, 2022). "By searching for DTGs associated with IRGs shared between COVID-19 and IS, we identified eight DEGs interacting with two known databases of drug targets: JAK2, ORM1, RNASE2, TNFSF13B, CYBB, EIF2AK2, CD79B and CAMP." (PMID 36969251, 2023). "Four genes: FCGR2A (FcRII–A), IRF9, OAS1 (2′–5′-oligoadenylate synthetase 1) and CYBB (also known as NOX2) were highlighted in the related pathways of coronavirus disease (COVID-19) from KEGG database." (PMID 36555339, 2022). "CYBB was found to be elevated in the peripheral blood mononuclear cells of patients with COVID-19." (PMID 38882332, 2024). "The following four genes were enriched in the related pathways of coronavirus disease (COVID-19) from KEGG database: FCGR2A (FcRII–A), IRF9, OAS1(2′-5′-oligoadenylate synthetase 1) and CYBB (NOX2)." (PMID 36555339, 2022). "COVID-19 and NAFLD progression may regulate ferroptosis through the CYBB-hsa-miR-196a/b-5p-TUG1 axis." (PMID 37335656, 2023). "For CVD + CKD + COVID-19, the targets were C3, TLR4, MAPK14, and CYBB." (PMID 34067609, 2021). "Therefore, we hypothesized that the ferroptosis during the progression of COVID-19 and NAFLD might be regulated through the CYBB-hsa-miR-196a/b-5p-TUG1 axis." (PMID 37335656, 2023).
ischemic stroke (34 papers, 2010 to 2025). A stroke disorder caused by obstruction of blood flow to the brain, due to thrombotic (local blood clot formation) or embolic (due to a blood clot or other material traveling from another site) event. "CYBB, also known as NADPHoxidase 2 (NOX2), is involved in the generation of reactive oxygen species (ROS) during ischemic stroke (IS) and is found to be significantly increased." (PMID 38736878, 2024). "ROC monofactor analysis demonstrated a good performance of HMOX1, STAT3, CYBB, and TLR4 in the diagnosis of ischemic stroke." (PMID 36506580, 2022).
lupus (32 papers, 2012 to 2024). "In adults, individuals with hypomorphic mutations in NCF2 (p67phox) and female carriers of CYBB (gp91phox) mutations can develop multi-organ autoimmunity such as systemic lupus erythematosus (SLE)." (PMID 39228435, 2024). "Primary immunodeficiency and olfactory transduction pathways were significantly enriched in the high CYBB subgroup, while histidine metabolism, systemic lupus erythematosus, and basal transcription factor were significantly enriched in the low CYBB subgroup." (PMID 37228444, 2023). "For example, female CYBB mutation carriers of CGD could develop systemic lupus erythematosus (SLE)-like disease, including photosensitive rash and aphthous ulcers, as a consequence of Lyonization, that can cause variable loss of gp91phox function." (PMID 36870198, 2023). "Defective clearance of apoptotic cells following LAP deficiency resulting from lack of CYBB/NOX2 or RUBCN in phagocytic cells predisposes mice to an autoimmune disease resembling systemic lupus erythematosus." (PMID 30403914, 2019). "The finding that RUBICON and CYBB have opposite effects on lupus-like disease was unexpected, since both proteins are thought to be required for LAP, and the absence of LAP is thought to promote lupus." (PMID 35192551, 2022).
Insulin resistance (30 papers, 2013 to 2026). Increased resistance towards insulin, that is, diminished effectiveness of insulin in reducing blood glucose levels. "In adipose tissue, CYBB/Nox2 contributes to adipose tissue inflammation and development of insulin resistance." (PMID 33167412, 2020).
Immunodeficiency (29 papers, 2014 to 2026). Failure of the immune system to protect the body adequately from infection, due to the absence or insufficiency of some component process or substance. "CYBB (cytochrome b-245 beta chain) is a component of cytochrome b-245, which has been found to be associated with immunodeficiency." (PMID 34034637, 2021). "XR-CGD, which is caused by a CYBB gene variant, is a congenital and hereditary immunodeficiency." (PMID 38306523, 2024). "Additionally, due to genetic variants, deletions of NCF1, NCF2, and CYBB can cause hereditary immune diseases." (PMID 36718447, 2023). "Mutations in 6 genes (IL12RB1, CYBB, IFNGR1, IL2RG, STAT1, and RAG1) account for 66% of BCG-associated immunodeficiency mutations." (PMID 41748971, 2026). "X-CGD is an immunodeficiency caused by mutations in the CYBB gene, which encodes the gp91phox protein." (PMID 37051232, 2023). "NADPH oxidase CYBB, required for ROS production, displayed an increased expression in SF neutrophils when compared to matched neutrophils from PB (RA, as well as in other immune diseases)." (PMID 37087463, 2023). "In 2011, an immunodeficiency without CGD features that was caused by a partial XR CYBB gene defect was described in seven male patients who developed BCGosis, recurrent BCG, or Mtb infections in two unrelated kindreds." (PMID 36569938, 2022). "The strong link to genetic defects (e.g., CYBB, RAG1 mutations) echoes findings in congenital immunodeficiency-associated IFI, suggesting that CA-IFI may warrant genetic testing even in the absence of classic immunodeficiency phenotypes." (PMID 40550072, 2025).
colitis (28 papers, 2008 to 2026). Inflammation of the colon. "Our results show that the NAMPT, TLR4, and CYBB genes associated with mouse colitis share functions with those of humans." (PMID 36552583, 2022). "Second, this is the first report, to our knowledge, showing that macrophage-specific eNAMPT functions as a protective factor to alleviate the severity of colitis through inhibiting the binding by macrophages of CYBB and TLR4 to circulating eNAMPT." (PMID 36552583, 2022). "Here our analyses of single-cell RNA-seq data revealed that the levels of NAMPT and CYBB/NOX2 in macrophages were elevated in patients with colitis and in mouse models of acute and chronic colitis." (PMID 36552583, 2022). "In colitis, CYBB cooperates with TLR4 to regulate the activation of the NLRP3 inflammasome." (PMID 40692778, 2025). "Notably, rCT-NAMPT has a partially therapeutic effect against acute DSS-induced colitis in TLR4−/− or CYBB−/− mice compared with WT mice." (PMID 36552583, 2022).
Autoimmunity (25 papers, 2015 to 2025). The occurrence of an immune reaction against the organism's own cells or tissues. "Further, female carriers of X-linked CGD, in which one X chromosome carries the normal functioning allele, while the second X chromosome harbors the mutant CYBB, are afflicted with high rates of autoimmunity and inflammatory disease, similar to their CGD counterparts." (PMID 40227295, 2025). "Given that our data contradict the published role for LAP in autoimmunity, we assessed whether CYBB and RUBICON are requisite for LAP." (PMID 35192551, 2022). "Since our results did not support the published role for LAP in autoimmunity, and in fact showed opposite roles for 2 proteins that are both thought to be critical for LAP, we reassessed whether CYBB and RUBICON are indeed requisite for LAP in macrophages." (PMID 35192551, 2022).
autoimmune disease (23 papers, 2017 to 2025). A disorder resulting from loss of function or tissue destruction of an organ or multiple organs, arising from humoral or cellular immune responses of the individual to their own tissue constituents. "Nevertheless, studies investigating the correlation between CYBB and autoimmune disorders such as Inflammatory Bowel Disease are scarce." (PMID 37465687, 2023). "The results showed that CYBB expression was increased in RA SLE, and AOSD, indicating CYBB may play an important role in autoinflammatory and autoimmune diseases through mediating oxidative stress of neutrophils." (PMID 37087463, 2023). "In addition, we also verified the mRNA expression of CYBB in neutrophils with autoinflammatory and autoimmune diseases." (PMID 37087463, 2023).
melanoma (22 papers, 2013 to 2025). A malignant, usually aggressive tumor composed of atypical, neoplastic melanocytes. "Mice deficient in the NOX2 subunit CYBB showed reduced lung metastasis of melanoma cells by downmodulating natural killer (NK)-cell function." (PMID 36829988, 2023). "CYBB was associated with poorer disease‐free survival and OS in melanoma." (PMID 35373463, 2022). "Previous studies have shown that NOX4 has the potential to promote the progression of non-small cell lung cancer (NSCLC), colorectal cancer, and pancreatic cancer while CYBB has been approved to enhance the metastasis of melanoma in mice." (PMID 39000203, 2024). "The genes of HAMP, SLC7A5, CYBB, and IFNG were highly expressed in melanoma cell lines, while JDP2, TUBE1, PROM2, GPX2, FBXW7, and ARNTL were lowly expressed in melanoma cell lines." (PMID 35373463, 2022). "Based on the TCGA database, we found that Wdfy4, CYBB, Itgb2, and Itgam were down-regulated and MMP2 was up-regulated in melanoma samples compared with normal samples." (PMID 33679872, 2020).
acute myeloid leukemia (21 papers, 2019 to 2025). Acute myeloid leukemia (AML) is a group of neoplasms arising from precursor cells committed to the myeloid cell-line differentiation. "CYBB activation can result in the accumulation of ROS and contribute to the development of a resistant phenotype in acute myeloid leukemia (AML)." (PMID 37175412, 2023). "In addition to upgraded expression levels of acute myeloid leukemia-related genes during leukemic transformation, expression levels of some inflammation-related genes (such as S100s, RNASE3, and CYBB) were also increased, and inflammation-related pathways were up-regulated." (PMID 34229751, 2021).
atrial fibrillation (18 papers, 2016 to 2025). A disorder characterized by an electrocardiographic finding of a supraventricular arrhythmia characterized by the replacement of consistent P waves by rapid oscillations or fibrillatory waves that vary in size, shape and timing and are accompanied by an irregular ventricular response. "Therefore, the diagnostic efficacy of CYBB, CXCR2, and S100A4 in different populations and its role in the occurrence of atrial fibrillation still need more external validation." (PMID 35305619, 2022).
type 2 diabetes (17 papers, 2017 to 2026). "The link between polymorphic genes involved in redox homeostasis, such as GCLM (rs2301022), GGT7 (rs6119534, rs11546155), GSTM1 (+/del), GSTP1 (rs1695, rs1138272), RAC1 (rs7784465), and CYBB (rs5917471), and type 2 diabetes differs in overweight and normal-weight individuals." (PMID 36902173, 2023).
multiple sclerosis (15 papers, 2017 to 2025). A progressive autoimmune disorder affecting the central nervous system resulting in demyelination. "Giulia Cardamone and his colleagues in the year 2018 found the altered expression of the CYBB gene resulting in the demyelination and axonal injury in both multiple sclerosis (MS) and experimental autoimmune encephalomyelitis in the murine model." (PMID 38956704, 2024). "All genes were downregulated in expression except RUNX3, which was upregulated in type 1 diabetes, and CYBB in multiple sclerosis." (PMID 38956704, 2024). "CYBB, and the NADPH oxidase gene, show gender-specific differential expression in multiple sclerosis." (PMID 33679872, 2020). "The CYBB and NADPH oxidase genes exhibited sex differential expression in multiple sclerosis." (PMID 35373463, 2022).
gastric cancer (14 papers, 2017 to 2025). A primary or metastatic malignant neoplasm involving the stomach. "CYBB is highly expressed in gastric cancer, and CYBB was identified as potential biomarkers in gastric cancer." (PMID 36973348, 2023).
fungal infections (13 papers, 2017 to 2025). "Patients with CYBB mutations often develop recurrent or severe bacterial or fungal infections, mostly in the lungs, skin, lymph nodes, and liver." (PMID 37434114, 2023).
glioma (13 papers, 2017 to 2025). A benign or malignant brain and spinal cord tumor that arises from glial cells (astrocytes, oligodendrocytes, ependymal cells). "In addition, radiotherapy exacerbated DNA damage by increasing mitochondrial ROS levels, whereas glioma cells with high CYBB expression inhibited ROS accumulation by activating the Nrf2/SOD2 pathway, thereby enhancing resistance to radiotherapy." (PMID 40452834, 2025). "In gliomas exhibiting Nrf2 overactivity, CYBB might control the expression of antioxidant enzymes involved in drug detoxification and alleviate redox stress." (PMID 37175412, 2023). "The identification of the downstream signals of HK2 demonstrated that the high expression of hub genes, including ITGB2, CD53, C3AR1, CYBB and ITGAM, maybe a potential target for the treatment of glioma." (PMID 35982398, 2022). "Moreover, multivariate Cox regression revealed that CYBB, CD53, SCRT1 and SYP might be independent factors for predicting the prognosis of gliomas." (PMID 35982398, 2022). "Moreover, further multivariate Cox regression analysis revealed that the expression of CYBB (P = 0.00087), CD53 (P = 0.04883), SCRT1 (P = 0.00071) and SYP (P = 0.02491) can be independent factors of the prognosis of gliomas and predict the survival of glioma patients." (PMID 35982398, 2022).
primary immunodeficiency (13 papers, 2015 to 2025). "X-linked recessive chronic granulomatous disease (XR-CGD) is a severe primary immunodeficiency principally caused by a CYBB (OMIM: 300481) gene variant." (PMID 38306523, 2024). "The primary immunodeficiency caused by mutations in the CYBB gene results in the inability of phagocytes to clear the infection." (PMID 37520121, 2023). "The X-linked form of CGD (X-CGD) is a rare primary immunodeficiency caused by mutations in the CYBB gene that encodes gp91phox, a subunit of NADPH oxidase 2 (NOX2)." (PMID 33535527, 2021). "In addition, the pathways altered by CYBB were related to B cell/T cell receptor signaling pathways, chemokine signaling pathway, and primary immunodeficiency (P < 0.05)." (PMID 37876929, 2023). "BTKbase led to the launch of related databases for several primary immunodeficiences (PIDs), including CD40 ligand, cytochrome b-245 beta chain (CYBB), IL2RG, WAS, and over 100 PID databases." (PMID 40225173, 2023).
ovarian carcinoma (12 papers, 2018 to 2025). A malignant neoplasm originating from the surface ovarian epithelium. "In conclusion, our study found that low p27 expression in ovarian cancer tissues correlates with chemoresistance, and that p27 overexpression triggers ferroptosis by transcriptionally activating CYBB, thereby enhancing cisplatin sensitivity in EOC cells." (PMID 41354340, 2025). "Downregulation or inactivation of CYBB in ovarian cancer cells has been shown to inhibit ferroptosis, thereby effectively promoting chemoresistance." (PMID 41354340, 2025). "CD83 highly-associated genes, such as ITGAM, IL1B, CYBB, PIK3R5, BTK, and OSM, ectopically express in ovarian cancer cells or tissues, involving in ovarian cancer progression, hypoxia networks, and the development of chemoresistance." (PMID 32823589, 2020). "Notably, CYBB showed a high frequency of deletions in various malignancies such as liposarcoma, bladder squamous cell carcinoma and severe ovarian cancer." (PMID 40895569, 2025). "In addition, through the literature review, we found that except CYBB, VDAC2, IDH1, MT1G, SLC1A4, PCK2, SLC3A2, the prognostic value of other FRGs in ovarian cancer has been reported, which provided a possibility for constructing a prognostic model." (PMID 36386203, 2022).
Duchenne muscular dystrophy (11 papers, 2016 to 2025). Duchenne muscular dystrophy (DMD) is a neuromuscular disease characterized by rapidly progressive muscle weakness and wasting due to degeneration of skeletal, smooth and cardiac muscle. "Examples include granulomatous disease (OMIM 306400) due to CYBB mutation, Duchenne muscular dystrophy (OMIM 310200) due to DMD mutation, and McLeod syndrome (OMIM 300842) due to XK mutation." (PMID 39000307, 2024).
myocardial ischemia (10 papers, 2015 to 2024). A disorder of cardiac function caused by insufficient blood flow to the muscle tissue of the heart. "In the present study, XML pretreatment was shown to mitigate the upregulation of myocardial ischemia induced by CYBA/CYBB levels." (PMID 35141226, 2022).
Granuloma (9 papers, 2014 to 2026). A compact, organized collection of mature mononuclear phagocytes, which may be but is not necessarily accompanied by accessory features such as necrosis. "The mice deficient in the innate immunity adapter proteins MyD88 and cytochrome B-245 beta chain (CybB) had larger and more granulomas compared to the wild-type mice injected with P. acnes." (PMID 33173621, 2020). "Larger granulomas were also observed in mice lacking the CybB/Nox2 gene when exposed to Propionibacterium acnes." (PMID 40002701, 2025).
asthma (8 papers, 2012 to 2025). "In conclusion, CYBB, EPAS1, CBS, G6PD, and STAT3 demonstrate strong diagnostic potential for asthma." (PMID 40165005, 2025). "CYBB (AUC ═ 0.82), EPAS1 (AUC ═ 0.839), CBS (AUC ═ 0.804), G6PD (AUC ═ 0.86), and STAT3 (AUC ═ 0.873) demonstrate high diagnostic accuracy for asthma (AUC > 0.8)." (PMID 40165005, 2025). "Our investigation also identified important genes involved in ferroptosis and asthma, including EPAS1, STAT3, G6PD, CYBB, and CBS." (PMID 40165005, 2025).
osteoporosis (7 papers, 2016 to 2025). A condition of reduced bone mass, with decreased cortical thickness and a decrease in the number and size of the trabeculae of cancellous bone (but normal chemical composition), resulting in increased fracture incidence. "A 5-gene combination (CCR1, CD33, HCK, LILRB2 and CYBB) was established as an optimal and effective biomarker for osteoporosis using SVM with feature selection and classification procedures." (PMID 34622712, 2021).
sarcoidosis (7 papers, 2006 to 2024). Sarcoidosis is a multisystemic disorder of unknown cause characterized by the formation of immune granulomas in involved organs. "generated a mouse model of GI using a strain of P. acnes isolated from a patient with sarcoidosis, and showed that a deficiency in CYBB is linked with increased granuloma formation in the lung." (PMID 35846773, 2022). "Since NADPH is oxidized by NOX to generate ROS, we examined the expression of NOX in macrophages using scRNA-Seq data and found that NOX2 (CYBB) was expressed in macrophages in sarcoidosis skin as previously reported." (PMID 38038136, 2023). "The relative gene expression levels for ATP6AP1, CYBB, LAMP2, and SERPINA1 were significantly higher in sarcoidosis monocytes as compared to healthy monocytes." (PMID 28577019, 2017).